SP1 (Sp1 transcription factor)
Diseases named in the same sentence as SP1 in open-access papers (continued):
Sharing a sentence is not in itself a finding about the gene and the disease.
Cerebral ischemia (12 papers, 2014 to 2023). Restriction of arterial blood supply to the brain associated with insufficient oxygenation to support the metabolic requirements of the tissue. "It has been reported that Sp1 can be cross-linked by increased transglutaminase expression in neuronal cell nuclei under conditions of brain ischemia." (PMID 26703734, 2015). "Further examination of the Sp1 promoter using luciferase reporter assays and chromatin immunoprecipitation after cerebral ischemia revealed that Hif binds to Hif-binding sites on the rat Sp1 promoter to stimulate transcription of the Sp1 gene." (PMID 34769328, 2021). "Accordingly, REST has been shown to form a histone deacetylase complex that is a director repressor of SP1 in cerebral ischemia, a TF we identify as varying significantly over space, in the opposite direction of REST37." (PMID 33627658, 2021). "Subsequently, the mice were subjected to cerebral ischemia and reperfusion, and Sp1 gene expression was quantified on day 3 after MCAO induction." (PMID 34118948, 2021). "Redox-responsive transcription factor sp1, which is dysregulated in AD and cerebral ischemia, reportedly upregulates the expression of ACSL4 by directly binding to the ACSL4 regulatory region." (PMID 34689160, 2021). "For instance, a recent investigation has demonstrated that SP1 is involved in miR-183-5p-IκB-α signaling pathway, thereby contributing to cerebral ischemia." (PMID 30971889, 2019). "Indeed, brain ischemia induced an up-regulation in HDAC9 protein levels that binds to the two transcription factors HIF-1 and Sp1 causing their deacetylation." (PMID 37324938, 2023). "Furthermore, Sp1 inhibition abolishes curcumin-induced Prdx6 upregulation following cerebral ischemia." (PMID 36290607, 2022). "Interestingly, the levels of certain miRNAs are altered during cerebral ischemia, and SP1 can serve as a target of these miRNAs related to stroke." (PMID 34970121, 2021). "The abundance of the wild-type C allele is approximately 30% more than that of the mutant T allele, and the t-PA enhancer-7351C > T SNP diminishes the affinity of SP1 for this locus, a change that reduces the release of t-PA and thus affects the final infarct size in cerebral ischemia." (PMID 34970121, 2021). "HIF-1α binds these HREs, thereby increasing Sp1 protein levels in conditions of cerebral ischemia." (PMID 26703734, 2015). "Taken together our study indicates that ERK1/2 and Sp1 could serve as potential pharmacological targets in aiding focal cerebral ischemia treatment." (PMID 25479176, 2014). "In the early stage of cerebral ischemia, hypoxia-inducible factor 1α (HIF-1α) and Sp1 transcription factor (Sp1) induce the upregulation of APJ expression." (PMID 35668778, 2022). "Given that SP1 elevates ETBR levels and exacerbates cerebral ischemia, relevant studies have confirmed that mithramycin A can be used to reduce ETBR expression on cerebral arterial smooth muscle after I/R." (PMID 34970121, 2021). "In addition, SP1 promotes NCX1 overexpression and attenuates brain edema, and the development of drugs that modulate NCX1 by promoting its upregulation in stroke or through epigenetic changes may be a novel pharmacological pathway to improve neuronal injury during cerebral ischemia." (PMID 34970121, 2021).
COVID-19 (12 papers, 2021 to 2024). A disease caused by infection with severe acute respiratory syndrome coronavirus 2. "The spike protein SP1 of the SARS-CoV-2 virus, which causes COVID-19, is a good target for discriminating VOCs and VOIs due to a few key reasons: (i) S1 protein enables the virus to enter host cells." (PMID 37895584, 2023). "Furthering potential relevance of the present results with regard to COVID-19, HBECs from a study population of asthmatic patients with different severity degrees were exposed to SP1 in this study (study population 2)." (PMID 34950134, 2021). "COVID-19-infected MS patients under treatment with SP1 or anti-CD20 therapies may show a lower immune responses against the virus particles." (PMID 35214735, 2022). "Tetramers containing these peptides could interact with specific CD8+ T cells from convalescent COVID-19 patients, and one dominant epitope (n-Sp1) was defined." (PMID 35116022, 2021). "By using HLA-A*0201 tetramers containing the mutated epitopes, no CD8+ T cells specific to n-Sp1 mutation were detected in HLA-A2-positive convalescent COVID-19 patients from Guangzhou, China." (PMID 35116022, 2021). "Combining the results of HLA-A*02:01 binding capability, the proportion of antigen-specific CD8+ T cells in HLA-A2-positive convalescent COVID-19 patients, and the ability to activate T cells, we therefore propose that n-Sp1 is the dominant CD8+ T-cell epitope specific to SARS-CoV-2." (PMID 35116022, 2021). "Analysis of the transcription factors using the TRRUST database from our data (212 DEGs from GSE36854 and GSE21001) for MPXV infection and COVID-19 database by Metascape identified JUN, REL, STAT3, NFKB1, RELA, SP1, and so on." (PMID 37006463, 2023). "MiR-21-5p and miR-22-3p, both upregulated in COVID-19 patients, target several genes involved in cell signaling, cell proliferation and angiogenesis (e.g., HIF1A, MYC, SP1, SMAD7, VHL)." (PMID 36032130, 2022). "Firstly, although SP1 was identified as a pivotal transcription factor in modulating ACE2 expression via the action of colchicine and MithA, neither of these compounds currently qualify as a candidate for the treatment of COVID-19." (PMID 38375778, 2024).
pancreatic ductal adenocarcinoma (11 papers, 2012 to 2023). An infiltrating adenocarcinoma that arises from the epithelial cells of the pancreas. "EMT can be induced by Sp1 in pancreatic ductal adenocarcinoma cells and the EMT program is known to promote drug resistance in cancer cells." (PMID 36499676, 2022). "Previous studies showed that celecoxib, a cyclooxygenase-2 (COX2) inhibitor, can inhibit angiogenesis and metastasis of pancreatic ductal adenocarcinoma (PDAC) via the suppression of specificity protein 1 (Sp1)." (PMID 27057636, 2016). "In regard to cancer, numerous previous studies have shown that Sp1 levels were elevated in various types of human cancers, including lung, colorectal, gastric and pancreatic ductal adenocarcinoma, correlating with aggressive biological activity and poor clinical outcomes." (PMID 29088790, 2017). "Using NetRank, we identified seven genes (STAT3, FOS, JUN, SP1, CDX2, CEBPA, and BRCA1) as most relevant for predicting survival in patients with pancreatic ductal adenocarcinoma." (PMID 22615549, 2012). "In pancreatic ductal adenocarcinoma (PDAC), elevated COX-2 expression promotes angiogenesis through EGFR/p38-MAPK/specificity protein-1 (Sp1)-dependent signaling, and inhibition of COX-2 leads to decreased angiogenesis and tumor growth in a VEGF-dependent manner." (PMID 37686525, 2023). "We studied whether SP1 exerts its effect on invasiveness and promotion of the epithelial-mesenchymal transition (EMT) by regulating lysyl oxidase-like 2 (LOXL2) in pancreatic ductal adenocarcinoma (PDAC) cell lines." (PMID 30976063, 2019).
thyroid cancer (11 papers, 2010 to 2024). "In the context of thyroid cancer, Sp1 displays distinctive expression patterns and has been identified as a participant in a positive feedback loop that regulates malignant characteristics." (PMID 37833989, 2023). "SP1 is often overexpressed in several human cancers, including gastric, breast, brain, lung, pancreatic, and thyroid cancers, and promoting tumor initiation and progression." (PMID 36870986, 2023). "Specificity protein 1 (Sp1), a transcription factor recognizing GC-rich DNA promoter, is overexpressed in many cancers such as breast, gastric, pancreatic, lung, brain, and thyroid cancers to promote tumor initiation and tumor growth." (PMID 35337344, 2022). "The third variant is an upstream variant in the DAPL1 gene, shown to affect the binding sites of MAZR and Sp1, a potential tumor suppressor in thyroid cancer, by SNPnexus and Segway." (PMID 31614935, 2019). "Nevertheless, the remarkable positive correlation between SP1 and IKKα expression, and the significant negative correlation between SP1 and CRSP8 expression in thyroid cancer denied such possibility." (PMID 33162555, 2021).
oral cancer (10 papers, 2013 to 2024). "Dehydroandrographolide, another major compound extracted from A. paniculata, significantly reduces the expression of TFs, c-Fos, c-Jun, and SP1 in SCC9 cells (an oral cancer cell line)." (PMID 37958849, 2023). "The downregulation of Sp1 inhibited the growth of SCC-15 and YD-15 oral cancer cells, whereas D. chinensis inhibited cell growth and induced apoptosis in both cell lines by decreasing the expression of Sp1." (PMID 35062995, 2022). "A recent study in our laboratory has shown that Sp1 is over-expressed in oral cancer tissues compared with normal oral tissues." (PMID 23403540, 2013). "The present study demonstrates that methanol extracts of C. officinale Makino (MECO) and C. bursa-pastoris (MECB) decrease cell growth and induce apoptosis via the downregulation of Sp1 in HSC-2 human oral cancer cells." (PMID 23403540, 2013). "In conclusion, the results of the present study indicate that MECO and MECB treatment inhibited cell growth and induced apoptosis via the downregulation of Sp1 in HSC-2 human oral cancer cells." (PMID 23403540, 2013). "Baicalein suppresses the growth of oral cancer cells via an Sp1/NF-κB-dependent mechanism." (PMID 36432119, 2022). "Sp1 plays a critical role in epithelial development, and Klf4−/− mice develop oral carcinomas." (PMID 26847634, 2016). "In the present study, we examined whether MECO and MECB inhibit cell growth and induce apoptosis through the downregulation of Sp1 in oral cancer cells." (PMID 23403540, 2013). "Notably, several naturally occurring compounds decreased the cell growth of oral cancer cells, and exhibited apoptotic activity through the decreased expression of Sp1 and regulation of its downstream target proteins." (PMID 23403540, 2013). "Therefore, we provide experimental evidence to indicate that MECO and MECB may be attractive anticancer drug candidates targeting Sp1 in oral cancers." (PMID 23403540, 2013). "Overexpression of SP1 has been observed in HNSCC as compared to normal oral mucosa, and its inhibition downregulates growth in oral cancer cell lines." (PMID 33344262, 2020). "SP1 regulates the metastasis in LSCC, promotes cell migration and invasion in OSCC by upregulating Annexin A2 transcription, and downregulation of SP1 inhibits the growth of oral cancer cell SCC-15, YD-15." (PMID 33344262, 2020).
renal fibrosis (10 papers, 2013 to 2025). A final common manifestation of a wide variety of chronic kidney diseases characterized by glomerulosclerosis and tubulointerstitial fibrosis. "Overall, SP1 is an important pro-fibrotic target for renal fibrosis, and many treating strategies based on SP1 has been developed until now." (PMID 39850832, 2025). "In vitro and in vivo data suggest that Sp1 participates in renal fibrosis by promoting TGF-β expression in normal rat kidney NRK-49F fibroblast cells and mesangial cells." (PMID 38256157, 2024). "Further in vitro tests indicated that these miRNA combinations enhanced pre-fibrotic molecules via the SP1 and Smad3/TGFβ pathways, promoting renal fibrosis." (PMID 39104393, 2024). "In summary, our study provides the first evidence that circUBXN7/IGF2BP2/SP1 formed RNA-protein complex, which improves mRNA stability of SP1 and the expression of SP1, promoting macrophage infiltration and renal fibrosis, accelerating the progression of DKD." (PMID 37744330, 2023). "As reduced Klotho expression was observed in renal fibrosis, we wondered the effects of Sp1 knockdown on renal fibrosis markers." (PMID 32571212, 2020). "In vitro experiments suggest that these miRNA combinations promote renal fibrosis by increasing profibrotic molecules through SP1 and Smad3/TGFβ pathways." (PMID 31349698, 2019). "These demonstrated that Sp1 knockdown could induce renal fibrosis by downregulation of Klotho in RTECs." (PMID 32571212, 2020). "Enhanced Sp1-TGF-β1/Smad3-NF-κB signaling may be the major mechanistic pathway by which deletion of Smad7 promotes ANG II-mediated renal fibrosis and inflammation." (PMID 23301086, 2013). "Taken together, the present study revealed that enhanced Sp1-TGF-β1/Smad3-NF-κB signaling and loss of miR-29 may be mechanisms by which deletion of Smad7 promotes ANG II-mediated renal fibrosis and inflammation." (PMID 23301086, 2013). "Besides, in renal fibrosis, miR-29c/Sp1 signals could inhibit type I collagen production under TGF-β1-stimulated kidney fibrosis." (PMID 27829234, 2016). "Interestingly, the protein levels of renal fibrosis markers, including α-SMA, fibronectin and E-cadherin, were remarkably altered by Sp1 knockdown in HK-2 cells." (PMID 32571212, 2020). "Whereas, deletion of Smad7 may result in a further increase in Sp1-Smad3 interaction, thereby enhancing ANG II-mediated renal fibrosis." (PMID 23301086, 2013). "The authors suggest that upregulation of Sp1 may promote the inflammatory process in the proliferative glomerulonephritis, but later stages of renal fibrosis may be independent of Sp1." (PMID 38256157, 2024). "Thus, ANG II-induced up-regulation of Sp1 expression and activation of Smad3 may cooperate in the development of ANG II-induced renal fibrosis as seen in WT mice." (PMID 23301086, 2013).
schizophrenia (10 papers, 2007 to 2025). A major psychotic disorder characterized by abnormalities in the perception or expression of reality. "A study investigating the effect of such factors on Sp1 transcriptional activity and on the expression of complex I subunits as well as on other genes implicated in schizophrenia, is underway." (PMID 17786189, 2007). "Interestingly, Sp1 is involved in the regulation of several genes which have been implicated in schizophrenia such as reelin, GAD67, MAOA/B, NMDA receptor subunits NR1 and NR2A/B, GABA A and DA receptors D1A and D2/3." (PMID 17786189, 2007). "In conclusion, the results of the present study, demonstrating disrupted expression of Sp1 associated with parallel impairments in complex I subunits, for which Sp1 is probably a transcription factor, suggest a key role for Sp1 in the pathogenesis of schizophrenia." (PMID 17786189, 2007). "Herein we show for the first time that in schizophrenia Sp1 mRNA levels are altered in three different brain areas and in the periphery in a region specific manner." (PMID 17786189, 2007). "This study, together with previous findings showing that SP4 and SP1 control the expression of D2 receptor in the cerebellum in schizophrenia, suggests a possible role of the transcription factors SP1 and SP4 in this circuit from the cerebellum to prefrontal cortex." (PMID 38919799, 2024). "In this subnetwork, SP1 has been reported to be abnormally expressed in schizophrenia." (PMID 25522158, 2014). "Consistent with the reduced expression of SP1 gene in schizophrenia, reduced expression of mouse Sp4 gene resulted in both hippocampal abnormalities and deficient sensorimotor gating, two putative endophenotypes for schizophrenia and related psychiatric disorders." (PMID 19401786, 2009). "Taken together, the results of this study in human subjects suggest that a defect in Sp1 transcriptional activity may play an important role in the abnormal expression of complex I subunits in schizophrenia." (PMID 17786189, 2007). "We therefore assume that disrupted Sp1 transcriptional activity is associated with schizophrenia pathology rather than its treatment." (PMID 17786189, 2007). "Indeed, in the present study we show that the expression of the ubiquitously expressed transcription factor Sp1 is altered in schizophrenia, in brain and in lymphocytes, as compared with normal controls." (PMID 17786189, 2007). "In order to further study whether Sp1 plays a role in the regulation of genes abnormally expressed in schizophrenia, we chose the NDUFV2 subunit of complex I, which was the most substantially affected in schizophrenia in both brain and periphery." (PMID 17786189, 2007). "Mithramycin induced a time dependent decrease in mRNA and protein levels of complex I subunits NDUFV1, NDUFV2 and NDUFS1, as well as of reelin, which was arbitrarily chosen as a gene known to be modulated by Sp1 and repeatedly reported to be abnormally expressed in schizophrenia." (PMID 17786189, 2007). "Sp1 mRNA expression was also altered in brain and in lymphocytes in schizophrenia." (PMID 17786189, 2007). "We investigated whether the ubiquitous transcription factor Sp1 is abnormally expressed in schizophrenia, and consequently can affect the expression of genes implicated in this disorder." (PMID 17786189, 2007). "Sp1 was abnormally expressed in schizophrenia in both brain and periphery." (PMID 17786189, 2007). "In contrast to Sp1/Sp4 transcription factors that recognize the GC-boxes in the proximal promoter region (−140,−41), the GC-boxes more upstream of this region can be bound by other transcription factors such as RB1CC1, another high-risk gene for schizophrenia from the SCHEMA." (PMID 34750502, 2022). "However, decreased expression of human SP1 gene, functionally redundant with its family member SP4 gene, was reported in the prefrontal cortex and striatum of postmortem brains of schizophrenia patients." (PMID 19401786, 2009).
schizophrenia (continued). "This opposite alteration in Sp1 expression in different brain regions is not unique for schizophrenia." (PMID 17786189, 2007). "SP1 can regulate gene FE65, which act as a ligand of Alzheimer’s disease amyloid precursor protein, and SP1 can promote the expression of SNAP-25, which is involved in the pathogenesis of neuropsychiatric disorders, including schizophrenia, attention deficit hyperactivity disorder and AD." (PMID 31422384, 2019). "However, the expression of human SP1 gene, which functionally substitutes with SP4 gene by recognizing the same DNA binding motif, was found to be reduced in both prefrontal cortex and striatum of postmortem brains of schizophrenia patients." (PMID 19401786, 2009).
triple-negative breast carcinoma (10 papers, 2018 to 2025). An invasive breast carcinoma which is negative for expression of estrogen receptor (ER), progesterone receptor (PR), and human epidermal growth factor receptor 2 (HER2). "The complete loss of both ER and PR led to the generation of a triple-negative breast cancer (TNBC) phenotype in fractions originating from SP1, SP2, and MP2." (PMID 36834918, 2023). "Lnc- AFAP1 antisense RNA 1 (AFAP1-AS1) can promote tumor progression and invasion by regulating the miR-2110/Sp1 axis in triple-negative breast cancer." (PMID 35156508, 2022). "Importantly, our data also show the cooperative regulation of RhoU, and of RhoU-mediated triple negative breast cancer cells migration and invasion, by WNT/JNK1/SP1 and STAT3." (PMID 30654518, 2019).